ALK (ALK receptor tyrosine kinase)
Diseases named in the same sentence as ALK in open-access papers (continued):
Sharing a sentence is not in itself a finding about the gene and the disease.
neuroblastoma (continued). "I1171T is a gain-of function ALK mutation, located in the neuroblastoma mutation hotspot of ALK, at the αC-helix in the amino-terminal lobe of the kinase." (PMID 35582571, 2019). "We show that alectinib inhibits growth in neuroblastoma cell lines, cells expressing neuroblastoma specific ALK mutations and also in exogenously expressed ALK activity in mouse model xenografts." (PMID 31334113, 2019). "Taken together, our preclinical results show that alectinib is more efficient than crizotinib in the inhibition of ALK mutant variants observed in neuroblastoma patients." (PMID 31334113, 2019). "Mutations of the tyrosine kinase ALK were firstly identified in neuroblastoma as the main cause of rare, familial cases of the disease." (PMID 35582571, 2019). "In a subset of neuroblastoma cases, several ALK mutations have been described within the same tumor." (PMID 31452835, 2019). "Our results show that repotrectinib is capable of inhibiting signaling activity of a range of ALK mutant variants found in neuroblastoma patients and importantly it exhibits strong antitumor effects in a xenograft model of neuroblastoma." (PMID 31852910, 2019). "The anaplastic lymphoma kinase (ALK) is the most frequent mutated gene detected in 7%–10% primary neuroblastomas." (PMID 30760980, 2019). "In conclusion, our work illustrates the complexity of the ALK mutation status in a subset of neuroblastoma cases and demonstrates the need for inhibitors able to counteract all activating mutations." (PMID 31452835, 2019). "In one patient with relapsed neuroblastoma with ALK F1174L mutation and ALK amplification, lorlatinib was used in a compassionate use program, and it showed some efficacy." (PMID 31747416, 2019). "Alectinib abrogated all neuroblastoma gain of function mutations investigated here, including ALK-G1128A, ALK-R1192P, and ALK-Y1278S in a similar manner as the hot spot mutations." (PMID 31334113, 2019). "In neuroblastoma, mutations in ALK can induce the phosphorylation of ALK target proteins and activation of downstream signaling pathways." (PMID 31852910, 2019). "This study also showed that NB1 (ALK amplified) and Kelly (ALK-F1174L) neuroblastoma cells were sensitive to alectinib, and that ALK kinase domains harboring the F1174L and R1275Q mutations were sensitive to alectinib in in vitro kinase assays." (PMID 31334113, 2019). "We have examined the ability of alectinib to abrogate the activity of different full length ALK gain-of-function mutations found in neuroblastoma cases, looking at neurite outgrowth, cell cycle progression and induction of apoptosis." (PMID 31334113, 2019). "The pathobiology of ALK amplification and ALK driver mutations for instance is well studied in the context of neuroblastoma." (PMID 31366041, 2019). "ALK aberrations in particular are now being factored into the new study protocols for treating high risk neuroblastoma." (PMID 30658459, 2019). "Our investigation of ALK gain of function mutation variants suggested an effective inhibition profile for alectinib as compared with crizotinib for all constitutively active neuroblastoma mutations with the exception of mutations at ALK-I1171." (PMID 31334113, 2019). "In this work, we characterized two neuroblastoma cell lines derived from the same patient at diagnosis exhibiting either the ALK F1174L mutation at a clonal level or both the ALK F1174L and L1196M mutations at different frequencies." (PMID 31452835, 2019). "We next examined the ability of repotrectinib to abrogate the phosphorylation activity of a panel of ALK mutant variants identified in neuroblastoma cases." (PMID 31852910, 2019). "Approximately 9% of neuroblastoma patients present germline or somatic aberrations in the gene encoding for anaplastic lymphoma kinase (ALK)." (PMID 31852910, 2019). "For example, our analysis of a high-risk neuroblastoma sample revealed outlier expression of the ALK (OMIM 105590) kinase and CDK6 kinase (eFigure 2 in the Supplement)." (PMID 31651965, 2019).
neuroblastoma (continued). "Whereas numerous ALK fusion genes have been reported in different malignancies, in neuroblastoma ALK is mainly activated through point mutations." (PMID 30778092, 2019). "Aberrations in ALK are associated with approximately 9% of all neuroblastomas including germline and sporadic cases and at an increased level in relapsed patients." (PMID 31852910, 2019). "In contrast, a study examining ALK mutations in cell lines derived from a patient with neuroblastoma at original diagnosis and at relapse." (PMID 35582583, 2019). "This increases in high-risk neuroblastomas, which have a 14% frequency of ALK aberrations at the time of diagnosis and show increasing numbers at relapse." (PMID 31852910, 2019). "All these ALK mutations were originally found in neuroblastoma cases and are located near the α-C-helix or the activation loop." (PMID 31852910, 2019). "Further large-scale screening studies confirmed that ALK mutations occur in approximately 8% of neuroblastoma patients at diagnosis, with three mutation hotspots at residues 1174, 1245 and 1275." (PMID 31452835, 2019). "Recently it was reported that mono treatment with ceritinib of a high-risk ALK neuroblastoma resulted in tumor shrinkage and the tumor was surgically removed." (PMID 31334113, 2019). "A recently described subset of approximately 10% of primary neuroblastoma tumors with ALK mutations has been shown to be driven through RET upregulation." (PMID 31695841, 2019). "ALK is frequently mutated in neuroblastoma and indeed the detected NM_004304.4_p.R1275L variant is a described hot spot locus within the kinase domain." (PMID 31466397, 2019). "ALK mutations are reported in an estimated 9% of neuroblastoma and recent reports indicate that the percentage of ALK-positive cases increases in the relapsed patient population." (PMID 31334113, 2019). "The ALK kinase in some neuroblastomas is activated as a result of gain-of-function mutations, ALK gene amplification, or copy number increase." (PMID 30813562, 2019). "Mutations in full length ALK found in neuroblastoma are observed within the kinase domain, and can influence the binding efficiency of the drug to inhibit activity and have implications for treatment choices and future drug combination strategies." (PMID 31334113, 2019). "Treatment of the neuroblastoma cell line, NB39nu, with the ALK inhibitors, crizotinib and alectinib, was associated to a marked downregulation of PD-L1 expression." (PMID 31480495, 2019). "The proliferative function of ALK is also achieved by constitutive activation, due to gene amplification or gain-of-function mutations, which are prevalent in approximately 10% neuroblastomas." (PMID 30813562, 2019). "High-risk neuroblastoma tumors were also found to have increased ALK gene expression when compared to low-risk tumors, further suggesting a potential role for ALK inhibitors in neuroblastoma therapy." (PMID 30384486, 2018). "For instance, amplification of MYCN is observed in approximately 20% of neuroblastoma cases and associated with poor prognosis, and ALK mutation is identified in nearly 1% of neuroblastoma cases." (PMID 30362960, 2018). "We selected one RTK, ALK, for subsequent studies, as the gene encoding for ALK was identified as a major familial neuroblastoma predisposition gene and can be targeted by US Food and Drug Administration (FDA)-approved drugs." (PMID 29515255, 2018). "ALK aberrations are found in 14% (10% mutations, 4% amplification) of high-risk neuroblastoma patients, and are biomarkers of poor outcome." (PMID 29515255, 2018). "ALK activation mutation and ALK amplification were reported in pediatric cancer neuroblastoma many years ago." (PMID 30400214, 2018).
neuroblastoma (continued). "ALK point mutations have been found mainly in neuroblastoma, as well as in NSCLC and ATC (anaplastic thyroid cancer)." (PMID 29455642, 2018). "Other oncogenic mechanisms leading to aberrant ALK activity include point mutations in the kinase domain and gene amplification, as observed in neuroblastoma and NSCLC amongst other cancers." (PMID 29642598, 2018). "Because up-regulated ALK expression is frequently associated with mutations in the kinase domain in neuroblastoma, we examined ALK exons 20-29 for mutations in all cases with ALK protein expression." (PMID 29755689, 2018). "While ALK gene amplification has been detected in a variety of tumours and gain-of-function mutations of ALK are described primarily in neuroblastoma, the most prevalent genomic ALK aberrations in human cancer are chromosomal rearrangements." (PMID 29455670, 2018). "On the other side, ALK mutation is found in 7% of sporadic neuroblastomas and 50% of familial neuroblastomas." (PMID 29455642, 2018). "Kinase pathways are also deregulated in neuroblastoma, including activating mutations of ALK, increased Akt signalling in stage 3 and 4 neuroblastoma, and relapsing neuroblastomas displaying mutations in the Ras-MAPK pathway." (PMID 29505958, 2018). "Approximately 10% of spontaneous cases of high risk neuroblastoma have anaplastic lymphoma kinase (ALK) mutations and nearly all cases of familial neuroblastoma." (PMID 30154341, 2018). "For example, point mutations and amplifications of ALK have been observed with high prevalence in the childhood cancer neuroblastoma." (PMID 29455675, 2018). "Accumulating evidence indicates that dysregulation of ALK is associated with numerous diseases such as anaplastic large cell lymphomas, lung cancer and neuroblastomas." (PMID 30004444, 2018). "ALK-activating point mutations predominate in neuroblastoma, making it an attractive therapeutic target." (PMID 29515255, 2018). "Another ALK mutation found commonly in neuroblastoma is R1275Q, which has been shown to increase the ATP-binding affinity in the mutated ALK in vitro." (PMID 29495603, 2018). "The combination of ceritinib and the CDK4/6 inhibitor, ribociclib, has been studied extensively in preclinical models of ALK mutated neuroblastoma." (PMID 30326621, 2018). "Further studies also reported that MYCN and common ALK mutations exert a role in neuroblastoma tumour initiation using neural crest progenitor cell lines MONC-1 and JoMa1." (PMID 30515222, 2018). "Since the R1275Q ALK mutation occurs frequently in neuroblastoma, we also tested combinatorial inhibition in LAN-5 cells." (PMID 29515255, 2018). "Preclinical studies of crizotinib have demonstrated that neuroblastoma with the F1174L mutation, the second most frequent ALK mutation observed in neuroblastoma, is resistant to single agent crizotinib." (PMID 30326621, 2018). "In a subsequent phase I trial, 79 children were enrolled and treated with the ALK inhibitor crizotinib, including 34 with neuroblastoma, 11 of which had known ALK mutations." (PMID 30384486, 2018). "Activating anaplastic lymphoma kinase (ALK) mutations are the most frequent cause of familial neuroblastoma." (PMID 29492199, 2018). "The RAS-MAPK pathway activating mutations detected in these relapsed neuroblastoma tumors include mutations in ALK, NF1, BRAF, PTPN11, FGFR1, KRAS, HRAS and NRAS." (PMID 30326621, 2018). "Mutations in the ALK gene are documented in 4–8% of sporadic neuroblastomas and account for the majority of hereditary cases; ALK variants contribute to the acquisition of neoplastic phenotype and are associated with overall poor-prognosis." (PMID 29495603, 2018). "ALK has since been associated with a plethora of human malignancies, including both familial and sporadic neuroblastoma, which is a childhood cancer of the sympathetic nervous system." (PMID 29084134, 2017).
neuroblastoma (continued). "Most neuroblastoma mutations are situated within the kinase domain of ALK, mainly located around the α-C-helix and the activation loop." (PMID 28030793, 2017). "The identification of ALK was hardly surprising given its established association with neuroblastoma." (PMID 28871274, 2017). "The Y1278S neuroblastoma mutation is sufficent to activate the ALK kinase domain, however the previously proposed regulatory Y1278:C1097 hydrogen bond is not important to maintain ligand-dependent activation." (PMID 29084134, 2017). "In this study, we assessed the antitumor activity of ceritinib in combination with NVP-CGM097, a potent and selective small molecule inhibitor of MDM2, in ALK-mutated or ALK-amplified neuroblastoma models." (PMID 28425916, 2017). "Previous reports revealed that the ALK expression level is higher in neuroblastomas with ALK mutation/amplification than in tumors with wild-type ALK." (PMID 29296183, 2017). "In a phase I study of pediatric cancer, 14 neuroblastoma patients with known ALK mutations were treated with ceritinib." (PMID 28425916, 2017). "Genomic analyses for pediatric neuroblastoma have identified recurrent somatic mutations in cancer-related genes such as ALK, PTPN11, ATRX, MYCN, and NRAS." (PMID 28521285, 2017). "ALK can be mutated or amplified in neuroblastomas and contributes to the neuroblastomas progression." (PMID 29018329, 2017). "Amplified ALK or mutated ALK was identified in ~14% of neuroblastomas (NB), the most common and aggressive childhood malignancy." (PMID 29143801, 2017). "Together, our results indicate that a sustained dephosphorylation of ALK at multiple phosphorylation sites by both crizotinib and ceritinib can be detected quantitatively by immunoassay in neuroblastoma cell lines with ALK mutations at F1174L or R1275Q." (PMID 28432815, 2017). "One of the first targeted treatment options to become available for chemoresistant neuroblastomas is targeting activating ALK mutations or amplifications by blocking ALK tyrosine kinase activity." (PMID 29156716, 2017). "To date, only two patients showed partial responses, and one patient with ALK F1174L mutated neuroblastoma had shrinkage of a retroperitoneal mass." (PMID 28425916, 2017). "Point mutations in full length ALK have been observed in both familial and sporadic neuroblastoma, a common childhood cancer which arises in the tissues of the sympathetic nervous system." (PMID 28030793, 2017). "Although the pathogenesis is not completely clear, it has been reported that many genetic susceptibility factors are associated with neuroblastoma such as the somatic mutation of ALK and the amplification mutation of N-myc." (PMID 29079782, 2017). "Of note, it is likely that such a therapeutic synergy benefit also takes place in ALK-mutated neuroblastoma, when combining PI3K/AKT/mTOR inhibition (using Rapamycin) and Crizotinib." (PMID 29186933, 2017). "In the rare cases where the neuroblastoma patients had objective responses, their tumor cells expressed the ALK R1275Q mutation." (PMID 28425916, 2017). "For example, ALK mutations are frequently observed in MYCN-amplified neuroblastomas, and most of ALK amplifications co-occur with MYCN amplification." (PMID 28425916, 2017). "Among these loci, the R1275Q mutation is the most common germline ALK mutation, occurring in about 45% of hereditary neuroblastomas." (PMID 28055978, 2017). "All these four ALK inhibitors displayed reduced anti-proliferative activity in the neuroblastoma cell lines that harbor the ALK F1174L mutation compared with NB-1." (PMID 28425916, 2017). "ALK was reported to be constitutively activated by gene amplification in several neuroblastoma cell lines, while neuroblastoma-specific mutations in ALK were suitable targets for development of several inhibitor therapeutics." (PMID 28163672, 2017).
neuroblastoma (continued). "This is in contrast to the ALK-F1174L positive control, which is a well characterised GOF ALK neuroblastoma mutation, that induced robust neurite outgrowth." (PMID 28030793, 2017). "Our panel of neuroblastoma cell lines harbor either the ALK F1174L or the ALK R1275Q mutation or express wild‐type ALK only and therefore represent two of the three hotspots of ALK mutation sites in neuroblastoma tumors." (PMID 28432815, 2017). "Characterization of the different point mutations in ALK observed in neuroblastoma patients has led to segregation of mutations into three classes; ligand independent, ligand dependent and kinase dead forms of receptor." (PMID 29084134, 2017). "Similar to MYCN, ALK amplification, and gain of function mutations are often correlated with poor outcome for neuroblastomas." (PMID 29018329, 2017). "The discovery of germline and somatic activating mutations in ALK provides a molecular rationale and a tractable target for treating neuroblastoma." (PMID 28425916, 2017). "R1275 accounts for 43% of ALK mutations in neuroblastoma, yet mutations at the F1174 locus (accounting for 30% of ALK mutations) are reported to have the strongest effect on nonphosphorylated ALK tyrosine kinase domain in vitro." (PMID 28432815, 2017). "Highly penetrant, heritable ALK mutations have been identified as the major cause of familial neuroblastoma." (PMID 28425916, 2017). "Activating mutations in full length anaplastic lymphoma kinase (ALK) have been reported in neuroblastoma and in anaplastic thyroid cancer." (PMID 28030793, 2017). "Point mutations activating the ALK tyrosine kinase domain were found in familial and sporadic neuroblastomas with high frequency." (PMID 27655666, 2016). "ALK mutation occurs in about 5-7% of neuroblastoma cases but this percentage is increased significantly in the relapsed patient population where approximately 20-25% of patients have ALK mutations." (PMID 27049722, 2016). "Overall, mutations at codons F1174, R1275 and F1245 together account for ∼85% of reported ALK mutations in neuroblastoma." (PMID 27888620, 2016). "Taken together, our results suggest PF-06463922 is a potent inhibitor of crizotinib-resistant ALK mutations, and highlights an important new treatment option for neuroblastoma patients." (PMID 27483357, 2016). "A number of attempts have been made to target pathways and expression factors in neuroblastoma including mutated ALK and GD2 expression with modest success." (PMID 27821095, 2016). "Our current study used quantitative phosphoproteomics to provide a global insight to the downstream pathways regulated by different ALK variants in neuroblastoma." (PMID 27732954, 2016). "About 40 % of high-risk neuroblastoma contain gene amplification of the transcription factor MYCN often leading to high Mycn expression whereas about 6 % of neuroblastomas contain mutation of ALK, the majority seen in connection to MYCN gene amplification." (PMID 27036398, 2016). "A few resistance mutations overlap with neuroblastoma ALK mutations from familial and somatic cases that are located at or near residues important for kinase activation, such as the activation loop and the αC helix." (PMID 27483357, 2016). "T1151M was identified recently in neuroblastoma patients and we present here the first report of this mutation in the ALK-fusion context, arising in a cell line grown in ceritinib." (PMID 27009859, 2016). "In neuroblastoma the most common and aggressive modified ALK variant (ALKF1174L) is necessary for cellular proliferation and survival." (PMID 27655666, 2016). "One proposed explanation for this difference is that membrane-associated point mutated/amplified ALK is found in neuroblastoma, while cytoplasmic ALK fusion proteins are found in other tumors." (PMID 27732954, 2016).